PLAGL2 (PLAG1 like zinc finger 2)
Diseases named in the same sentence as PLAGL2 in open-access papers (continued):
Sharing a sentence is not in itself a finding about the gene and the disease.
liver cancer (1 paper, 2021). An epithelial or non-epithelial malignant neoplasm that arises from the liver. "To confirm the relevance of PLAGL2 and C‐MET in HCC progression, we analyzed the mRNA data of TCGA liver cancer cohorts (LIHC) using the UALCAN web tool." (PMID 34586726, 2021).
lymph node tumor (1 paper, 2018). "Strong staining of PLAGL2 was more common in the larger, multiple, high-grade, high stage, and positive lymph node tumor specimens." (PMID 29662235, 2018).
malnutrition (1 paper, 2025). Inadequate nutrition resulting from poor diet, malabsorption, or abnormal nutrient distribution. "As an indication of malnutrition and resultant wasting syndrome, elevated asparagine synthetase (Asns) and reduced insulin growth factor 1 (Igf1) expression in livers from LEC Srebf2–/– mice were found, which resemble Plagl2-knockout mice in which lacteals in jejunum are also dilated." (PMID 41122969, 2025).
seborrheic dermatitis (1 paper, 2021). A chronic, inflammatory skin disorder that affects the scalp, central face and skin folds; it is characterized by scaling and itching. "In the present study, we identified that SeS2, a compound typically found in lotion form and mainly used to treat seborrheic dermatitis and tinea versicolor, induced growth inhibition and mitochondrial apoptosis of HCC cells in vitro and in vivo in a PLAGL2‐dependent manner." (PMID 34586726, 2021).
Sepsis (1 paper, 2012). Sepsis is defined as life-threatening organ dysfunction caused by a dysregulated host response to infection. "Transcriptional regulators like PLAGL2, EBF1, TCF7, KLF10 and SBNO2, previously not described in sepsis, are differentially expressed at early and late time points." (PMID 23009705, 2012).
tumor (33 papers, 2013 to 2025). "Taken together, these results reveal that chronic stress is associated with the upregulation of PLAGL2 and tumor metastasis." (PMID 38689092, 2024). "PLAGL2 has been identified as the cause of various cancer tumorigeneses and has oncogenic and tumor suppressor activities in different cancers." (PMID 35222518, 2021). "Consistent with their roles as oncogenes, Plag1 and Plagl2 promote proliferation, anchorage-independent growth, loss of contact inhibition and tumor formation in mice." (PMID 30361413, 2018). "By performing KEGG and Gene Oncology analyses, we found that the increase in PLAGL2 expression in depressed patients was associated with tumor metastasis pathways, including pathways related to extracellular matrix organization, cell-substrate adhesion, and negative regulation of cell adhesion." (PMID 38689092, 2024). "Notably, high PLAGL2 expression was significantly linked to tumor invasion depth (P = 0.033) and lymph node metastasis (P = 0.003)." (PMID 33391500, 2021). "The PLAGL1- and PLAGL2-amplified tumors formed separate sub-clusters within the same overarching tumor type—ET, PLAGL." (PMID 40751809, 2025). "For instance, the PLAGL2 and the PIK3CB were identified as key hub gene within the regulatory network that significantly associated with tumor immune infiltration and sensitivity of chemotherapeutic drugs for cancer." (PMID 38971948, 2024). "All of the PLAG-family tumors in this series were well-defined with involvement of the adjacent dura/meninges, occurring as large (> 5 cm) supratentorial tumors, except for the one tumor with PLAGL2 amplification located in the cerebellum." (PMID 39228008, 2024). "Desmin expression was present in the majority of evaluated tumors (9/12, 75%), which ranged from rare scattered cells to diffuse strong labeling of all tumor cells in a small number of the PLAGL2-amplified cases." (PMID 36437415, 2023). "Gene expression profiles of 11 tumors with amplification of PLAGL1 (n = 5) or PLAGL2 (n = 6) were compared to gene expression profiles of a total of 279 tumor samples from various other CNS tumor types and normal tissues." (PMID 36437415, 2023). "Tumor formation in nude mice demonstrated METTL14/PLAGL2/β-catenin axis promoted NSCLC development in vivo." (PMID 36873735, 2023). "Analysis based on exploration of the clinical predictive value showed PLAGL2, ZNF337 and ALG10 were significantly associated with tumor immune infiltration, different immune-related genes and sensitivity of chemotherapeutic drugs." (PMID 36879254, 2023). "Through a literature search, we found PLAGL2 regulated β-catenin and its downstream pathways and promoted tumor genesis and development." (PMID 36873735, 2023). "Next, we then performed a correlation analysis between PLAGL2 and tumor-infiltrating immune cells, including B cells, CD4+T cells, CD8+T cells, macrophages, neutrophils, and DCs by the TIMER database in GBM patients to evaluate the immunotherapy effect." (PMID 35222518, 2021). "The results showed that PLAGL2 was overexpressed in HCC tumor samples compared to that in normal samples." (PMID 34586726, 2021). "In this cohort, we found that PLAGL2 expression was considerably upregulated in HCC tumor tissues compared to that in adjacent non‐tumor tissues." (PMID 34586726, 2021). "To further characterize the relationship of PLAGL2 expression level and tumor specimens, we explored the expression levels of PLAGL2 in the GEO database (GSE4290)." (PMID 35222518, 2021). "An experimental lung metastasis assay was performed to assess the in vivo role of PLAGL2 in tumor metastasis." (PMID 33391500, 2021). "Among these genes, only DYRK1A, VPS4B, PLAGL2, these three genes have been reported to act as tumor-promoter in HCC." (PMID 33596983, 2021). "To extend the in vitro results, we explored the effect of PLAGL2 on tumor growth using a xenograft model." (PMID 33391500, 2021).
tumor (continued). "Taken together, PLAGL2 plays a critical role in tumor apoptosis resistance through C‐MET/STAT3 activation." (PMID 34586726, 2021). "By analyzing the correlation between PLAGL2 expression and clinicopathological features in HGG patients, we found that PLAGL2 expression was only associated with tumor grade." (PMID 35222518, 2021). "Here, we found that PLAGL2 expression was upregulated in HCC tumor tissues and that PLAGL2 overexpression substantially promoted apoptosis resistance in HCC cells." (PMID 34586726, 2021). "The elevated PLAGL2 expression markedly promoted tumour growth in vivo compared to that of the controls." (PMID 31827238, 2020). "All these studies suggested that PLAGL2 plays a role in tumor penetration, metastasis and eventual patient survival." (PMID 29662235, 2018). "The Plag gene family has three members; Plagl1/Zac1, which is a tumor suppressor gene, and Plag1 and Plagl2, which are proto-oncogenes." (PMID 30361413, 2018). "We also showed that the overexpression of PLAGL2 is correlated with tumor size, multiplicity of tumors, pathological grade, tumor cT, and lymph node metastasis." (PMID 29662235, 2018). "Other studies have shown that PLAGL2 was highly expressed in a variety of tumors and promoted tumor progression and metastasis." (PMID 29662235, 2018). "The overexpression of PLAGL2 was positively correlated with tumor size, multiplicity of tumors, tumor grade, tumor cT, and LNS, (P < 0.05)." (PMID 29662235, 2018). "PLAGL2 was upregulated in 72.0% (18/25) tumor tissues compared with the paired normal prostate tissues." (PMID 27537362, 2016). "On average, the PLAGL2 expression was significantly higher in tumor tissues than in adjacent normal tissues (P < 0.0001)." (PMID 27537362, 2016). "A large sample size and randomized study of PCa patients was needed to investigate the PLAGL2 expression and its correlation with PCa tumor development and prognosis." (PMID 27537362, 2016). "PLAGL2 can act as either an oncogene by activating thrombopoietin receptor (Mpl) in hematopoietic progenitors or a tumor suppressor by initiating cell cycle arrest and apoptosis via p73 activation." (PMID 23593351, 2013). "We used hepatocyte-specific deletion of PLAGL2 in mice (PLAGL2f/f Alb-cre) to validate whether knocking down PLAGL2 could inhibit epinephrine-induced tumorigenesis and tumor progression in vivo." (PMID 38689092, 2024). "Tumor volume and weight increased after PLAGL2 was overexpressed." (PMID 36873735, 2023). "Researchers believed PLAGL2 was overexpressed in different malignant tumors, and it could facilitate tumor proliferation, migration, invasion, and self-renewal." (PMID 36873735, 2023). "Finally, tumor formation in nude mice was performed to verify the role of the METTL14/PLAGL2/β-catenin signaling axis." (PMID 36873735, 2023). "One tumor with PLAGL2 amplification (#A113—excluded from the core DNA methylation cohort due to QC issues, but with a clear signal for ET, PLAGL), harbored additional focal high-level amplifications of the MDM4 oncogene on chromosome 1q32.1 and the MYCN oncogene on chromosome 2p24.3." (PMID 36437415, 2023). "Determination of whether there is any connection between PLAGL2 amplification in this CNS embryonal tumor and expression of PHOX2B will require closer study." (PMID 35763016, 2022). "ILF3-AS1 plays tumor-promoting role in PTC via targeting miR-4306/PLAGL2 axis." (PMID 34176471, 2021). "Additionally, the overexpression of PLAGL2 was correlated with adverse clinicopathological characteristics, such as tumor grade." (PMID 35222518, 2021). "PLAGL2 expression was higher in HCC tumor tissues than in normal adjacent tissues." (PMID 34586726, 2021). "A strong expression of PLAGL2 was observed in the nuclei of tumor cells." (PMID 35222518, 2021). "The expression of PLAGL2 was elevated as the tumor grade increased." (PMID 35222518, 2021). "SeS2 treatment also downregulated PLAGL2 levels in SMMC‐7721 tumor tissues." (PMID 34586726, 2021).
tumor (continued). "Other studies have shown that PLAGL2, as a tumor suppressor gene, could also induce cell cycle block and the apoptosis of human promonocytic U937 cells by regulating the expression of the p73." (PMID 35222518, 2021). "Furthermore, 73.8% of cases with low miR‐378a‐3p expression (45/61 cases) in HCC tumor tissues showed a high level of PLAGL2, whereas only 24.1% of cases with high miR‐378a‐3p expression (7/29 cases) exhibited a high level of PLAGL2 (p < 0.01)." (PMID 33634974, 2021). "We found that knockdown of PLAGL2 significantly abrogated miR‐378a‐3p antagonism‐induced enhancement of β‐catenin signaling in SMMC‐7721 tumor cells (p < 0.01), suggesting that miR‐378a‐3p reduction‐triggered upregulation of PLAGL2 is functionally important for activation of β‐catenin in HCC cells." (PMID 33634974, 2021). "Furthermore, the involvement of EMT was further investigated by WB and IHC analysis, which were conducted with mouse tumours formed by corresponding cells, indicating that PLAGL2 promotes EMT in vivo." (PMID 31827238, 2020). "Overexpression of PLAGL2 was found to correlate with tumor size, number, grade, and stage." (PMID 29662235, 2018). "PLAGL2 was mainly expressed in the cytoplasm and nucleus of the tumor cells." (PMID 29662235, 2018). "Further work is needed to elucidate the role and function of PLAGL2 in tumor genesis." (PMID 29662235, 2018). "It is interesting that PLAGL2 possesses both oncogenic and tumor suppressive activity." (PMID 27537362, 2016). "The PLAGL2 could also inhibit the human myelomonocytic U937 cell proliferation via activation of p73 and p73 target genes, as a tumor suppressor gene." (PMID 27537362, 2016). "PLAGL2 has been shown to have both oncogenic and tumor suppressor activities in different tissues." (PMID 27537362, 2016). "One possibility is that amplification of PLAGL2 leading to tumor formation can only occur during a small spatiotemporal window during development when PLAGL2 is expressed, while amplification of PLAGL1 might be less temporally limited in terms of subsequent tumor formation." (PMID 36437415, 2023). "In addition, related studies have shown PLAGL2 could regulate β-catenin and its downstream pathways and promote tumor genesis and development." (PMID 36873735, 2023). "Overexpression of PLAGL2 in Bel‐7402 cells significantly stimulated tumor growth compared to that in vector‐transfected cells and facilitated the inhibitory effect of SeS2 on tumor growth, which was presented as the tumor volume and the final change in xenograft tumor weight." (PMID 34586726, 2021). "Moreover, GENT2 database analysis showed that PLAGL2 expression increases with tumor grade." (PMID 35222518, 2021). "The roles and mechanisms of PLAGL2 in tumor progression remain largely unknown." (PMID 30158634, 2018). "Furthermore, the overexpression of PLAGL2 was correlated with PCa tumor progression and might serve as a poor prognosis maker following radical prostatectomy." (PMID 27537362, 2016). "However, it has been reported that PLAGL2 also plays as a tumor suppressor." (PMID 27537362, 2016). "To investigate the effects of chronic stress on PLAGL2 expression and HCC progression, we subjected C57BL6N mice to chronic restraint stress and generated a Hepa1-6 subcutaneous tumor model and a BALB/c mouse model with subcutaneous H22 tumors." (PMID 38689092, 2024). "A nomogram was constructed using the TCGA READ dataset based on the expression of ALG10, PLAGL2 and ZNF337 and the clinical characteristics including age, gender, stage, tumor (T), lymph node (N) and metastasis (M) stage." (PMID 36879254, 2023). "While PLAGL1 has been suggested as a putative tumor suppressor gene, PLAG1 and PLAGL2 are presumed proto-oncogenes." (PMID 36437415, 2023).
tumor (continued). "We describe a novel, biologically distinct type of CNS embryonal tumor—ET, PLAGL—that is presumably driven by amplification and subsequent overexpression of PLAGL1 or PLAGL2, the only recurrent molecular event detected in these tumors." (PMID 36437415, 2023). "We found that MET expression was significantly higher in HCC tumor tissues than in 50 normal tissue samples, and a positive correlation between the expression of PLAGL2 and MET was observed in 15‐paried HCC tumor tissues (r = 0.5730, p < 0.01)." (PMID 34586726, 2021). "The immunostaining intensity of PLAGL2 and total/nuclear β‐catenin was much stronger in HCC tumor tissues with low miR‐378a‐3p expression than in those with high miR‐378a‐3p expression." (PMID 33634974, 2021). "Our study provided robust evidence that miR-214-3p acts as a tumor-suppressor gene to inhibit CRC cell proliferation and migration by regulating the PLAGL2/MYH axis." (PMID 32413870, 2020). "PLAGL2 combines with the Wnt6 promoter and activates the β-catenin-dependent Wnt signaling pathway, thereby stimulating various downstream target genes (such as MMP7, CCND1) and promoting tumor development." (PMID 38003292, 2023). "Herein, we investigated the expression patterns and prognostic values of PLAGL2 in patients with HGG by using various databases, including Tumor Immune Estimation Resource 2.0 (TIMER2.0), GENT2, ONCOMINE, GEPIA, Human Protein Atlas, and Gene Expression Omnibus datasets." (PMID 35222518, 2021). "Meanwhile, considering the GBM group, the analysis results showed that the expression of PLAGL2 was significantly correlated with gender (p < 0.01), but not with tumor locus and radiochemotherapy." (PMID 35222518, 2021). "Given that matrix metalloproteinase (MMP) family proteins and EMT-related proteins participate in tumor cell migration and invasion, we examined the transcript and protein level of MMP9, N-cadherin, Vimentin, and E-cadherin in cells with modified PLAGL2 expression levels." (PMID 33391500, 2021). "In conclusion, our study provided robust evidence that miR-486-5p acted as a tumor-suppressor gene to inhibit CRC cells' proliferation and migration through regulating PLAGL2/IGF2/β-catenin expression and served as a novel prognostic and diagnostic biomarker of CRC." (PMID 30305607, 2018). "Although PLAGL2 could induce apoptosis in some cell types, more evidence showed that PLAGL2 was upregulated in various cancers including CRC and contributed to tumor survival, progression, and metastasis." (PMID 30158634, 2018). "The animals were sacrificed, and the tumor tissue from stressed animals exhibited increased mRNA expression of the EMT-related genes Twist1, Twist2, Zeb1, Zeb2, Slug, and PLAGL2 and increased protein expression of PLAGL2, Ki67 (a proliferation marker), N-cadherin, and Vimentin." (PMID 38689092, 2024). "To further explore the functional significance of PLAGL2 in β‐catenin activation induced by miR‐378a‐3p downregulation in human HCC cells, we studied the effect of siRNA‐mediated PLAGL2 knockdown on β‐catenin signaling in SMMC‐7721‐antagomiR‐378a‐3p tumor cells." (PMID 33634974, 2021). "Moreover, we observed that PLAGL2 level was elevated in HCC tissues compared with adjacent non-tumor tissues (p < 0.0001)." (PMID 33596983, 2021). "A recent study reported that vimentin overexpression and the EMT were induced by PLAGL2 via Wnt/β-catenin signaling pathway in CRC, which stimulated the migration and invasion of tumor cells and may validate our findings that vimentin was related to lymph node metastasis in CRC." (PMID 29955607, 2018). "The expression of PLAGL2 was significantly correlated with WHO grade (p < 0.05), but not with gender, tumor locus, histology, cell origin, treatment regimen, and radiochemotherapy." (PMID 35222518, 2021). "Previous studies have indicated that the expression of PLAGL2 was significantly higher in CRC tissues than in adjacent normal tissues and correlated with the depth of tumor invasion." (PMID 32413870, 2020).